FAM234B (family with sequence similarity 234 member B)
Synonyms: KIAA1467
Tractability: Antibody: UniProt predicts a signal peptide or a membrane-spanning region. PROTAC: ubiquitination databases record sites on it; its protein half-life has been measured.
Gene: Protein-coding gene on chromosome 12 (13,044,185 to 13,142,521, forward strand). Ensembl gene ENSG00000084444.
Subcellular location: Membrane; Golgi outpost; Cytoplasm, cytoskeleton, microtubule organizing center
Subcellular location (Human Protein Atlas): Endoplasmic reticulum
Gene Ontology:
Molecular function: protein binding
Cellular component: postsynaptic Golgi apparatus; membrane; microtubule organizing center
Genetic constraint (gnomAD): Loss-of-function variants: 26 observed, 57.94 expected, observed/expected ratio (o/e) 0.45, 90% interval 0.33 to 0.62. The upper end of that interval is the gene's LOEUF score, 0.62, which puts it in group 2 of 6, group 1 being the genes least tolerant of losing a copy. Missense variants: 664 observed, 757.27 expected, observed/expected ratio (o/e) 0.88, 90% interval 0.82 to 0.94. Synonymous variants: 298 observed, 308.27 expected, observed/expected ratio (o/e) 0.97, 90% interval 0.88 to 1.06.
Homologues: Orthologues: chimpanzee FAM234B (98% identical), macaque FAM234B (97% identical), dog FAM234B (91% identical), rabbit FAM234B (89% identical), pig FAM234B (88% identical), guinea pig FAM234B (88% identical), mouse Fam234b (87% identical), rat Fam234b (87% identical), zebrafish fam234b (34% identical), Drosophila melanogaster CG6184 (20% identical), Drosophila melanogaster CG3618 (18% identical). Paralogues in human: FAM234A (22% identical).